IL17A (interleukin 17A)
Diseases named in the same sentence as IL17A in open-access papers (continued):
Sharing a sentence is not in itself a finding about the gene and the disease.
liver fibrosis (continued). "Among the various immune cells, CD68 + macrophages interact the most with lymphatic vessels and biliary epithelial cells with periportal IL-17A + cells and M1 macrophages were reported to be associated with postoperative cholangitis and liver fibrosis and clinical outcome." (PMID 39365460, 2024). "Here we aimed to define whether hepatocytes directly respond to IL-17A stimulation and are associated with the development of hepatic fibrosis." (PMID 28039485, 2017). "Furthermore, IL-17A and IL-17RA deficiency protects mice from liver fibrosis induced by CCl4 and bile duct ligation." (PMID 24223606, 2013). "Previous studies reported that the increase in the number of TH17 cells in AIH was associated with the degree of liver fibrosis, and in vitro studies also confirmed that deficiencies in IL-17A and IL-17A receptors could reduce the liver fibrosis caused by CCl4 and bile duct ligation in mice." (PMID 33489994, 2021). "Some studies revealed that γδT cells might inhibit fibrogenesis by inducing apoptosis of activated HSCs in a FasL-dependent manner, while others emphasized the pathogenic role of γδT cells through IL-17A-mediated enhancement of HSCs activation in CCl4-induced liver injury and liver fibrosis." (PMID 30930903, 2019). "Unexpectedly, T2L ablation worsened both carbon tetrachloride- and bile duct ligation-induced liver fibrosis, accompanied by increased IL-17A+ T3Ls, predominantly γδ T cells." (PMID 41811951, 2026). "IL-17A promotes the recruitment of neutrophils in the liver and favors liver fibrosis in the model of bile duct ligation in mice." (PMID 39996122, 2025). "In a mouse model of Bile Duct Ligation (BDL)-induced liver fibrosis, IL-17A antibody therapy reduced hepatocyte necrosis, decreased pro-inflammatory cytokines, and mitigated neutrophil and macrophage infiltration." (PMID 39995661, 2025). "Self-noncoding RNA-containing exosomes from HSCs can mediate the activation of TLR3, which can further exacerbate hepatic fibrosis by enhancing the production of IL-17A by γδ T cells." (PMID 40761743, 2025). "Future studies should aim to clarify the specific molecular mechanisms linking IL17A, lipid metabolism, and hepatic fibrosis in order to develop effective treatment approaches." (PMID 40332363, 2025). "IL-17A has been shown to stimulate the activation of HSCs and contribute to liver fibrosis by increasing the expression of pro-inflammatory cytokines, such as IL-6, IL-1β, and TNF-α, as well as pro-fibrotic factors like TGF-β and α-SMA." (PMID 39995661, 2025). "The IL-10/IL-17A ratio observed in our study, as well as the ratio of IL-10/IL-22, varied between various degrees of hepatic fibrosis (F0-F3)." (PMID 40918132, 2025). "Th17 cells, characterized by the production of IL-17A/F, contribute to neutrophil recruitment and liver fibrosis via the activation of HSCs." (PMID 40427086, 2025). "MAIT cells have been found to promote liver fibrosis by producing IL-17A to activate hepatic stellate cells, an important component of liver fibrosis." (PMID 39820040, 2025). "IL-17A-mediated immune responses significantly affect the hepatic microenvironment, advancing liver fibrosis and correlating positively with fibrosis severity." (PMID 39995661, 2025). "The increased level of IL-17A in liver fibrosis facilitates the influx of inflammatory cells, drives the expression of profibrogenic growth factors, and activates hepatic stellate cells in the liver." (PMID 39872534, 2024). "It has been observed that the inhibition of Th17 cell differentiation leads to a downregulation of IL-17A expression, subsequently mitigating hepatic fibrosis and pulmonary fibrosis." (PMID 39872534, 2024). "In response to T cell receptor (TCR) engagement, these cells were shown to secrete IL-17A and promote liver fibrosis." (PMID 37774007, 2023). "Some relevant inflammatory factors play an important role in chronic liver injury, and IL-17A is a key factor in liver fibrosis." (PMID 36761734, 2023).
liver fibrosis (continued). "The role of Tc17 cells for the progression of liver fibrosis is still unclear: IL-17A can contribute to the progression of liver fibrosis by activating hepatic stellate cells." (PMID 38567057, 2023). "And high IL-17A expression in chronic HBV infection contributed to the development of liver fibrosis and cirrhosis." (PMID 35144643, 2022). "It has been revealed that in the progression of liver fibrosis, IL-17A functions together with IL-22 to enhance TGF-β in hepatic stellate cells." (PMID 35739565, 2022). "In a CCL4-induced rat liver fibrosis model, BM-MSCs treatment reduced IL-17, IL-2 and IL-6 serum proteins and downregulated IL-17A and IL-17RA proteins in liver tissues." (PMID 35895169, 2022). "Humanized mice on high fat diet with induced NAFLD develop liver fibrosis that is mediated by CD4+IL17A+ cells." (PMID 34211477, 2021). "In experimental liver fibrosis, IL-17A activates both HSCs and KCs, and stimulates TNF-α, IL-6 and TGF-β secretion that further aggravate fibrosis." (PMID 34064375, 2021). "Recent data suggest that liver fibrosis is guided by type 3 inflammation with IL-17A at the top of the line." (PMID 34211477, 2021). "The results showed that liver fibrosis caused a significant increase in the proportion of CD4+ IFN-γ+ T-cells (Th1), CD4+ IL-17A+ T-cells (Th17), and CD4+ CD25+ Foxp3+ Tregs, compared with the control group (p < 0.05)." (PMID 34158112, 2021). "We propose to trace the interaction of three molecules (IL-17A, IL-22, RA) and assess the possible impact of this trio on the development of liver fibrosis." (PMID 34211477, 2021). "IL-17A (secreted by Vγ2T or Th17 T cells) also promotes the recruitment of neutrophils into the liver and promotes liver fibrosis induced by Schistosoma japonicum infection or bile duct ligation (BDL)." (PMID 33763069, 2021). "IL-17A activates the expression of the MMP-2 and MMP-9 in vitro, which are widely implicated in the progression of liver fibrosis." (PMID 34211477, 2021). "For example, hepatocytes secrete exosomes during liver injury, which mediate the activation of Toll-like receptor 3 (TLR3) in HSCs and thus exacerbate liver fibrosis by enhancing interleukin-17A (IL-17) production by γδ T cells." (PMID 34234100, 2021). "BM-MSCs inhibited liver fibrosis by decreasing the expression of IL-17A and IL-17RA and the serum levels of IL-17 in the liver." (PMID 35187072, 2021). "There is much evidence of the deleterious effects of IL-17A on the development of a liver disease, particularly liver fibrosis." (PMID 34211477, 2021). "In two different mouse models of hepatic fibrosis (bile duct ligation and carbon tetrachloride), the deletion of IL-17A, IL-23, and IL-17RA inhibited HSC activation and fibrosis development." (PMID 33123017, 2020). "During S. japonicum infection, Vγ2 γδ T cells prevent hepatic fibrosis by recruiting neutrophils and secreting IL-17A." (PMID 32132991, 2020). "IL-17A played critical role of HSC activation for liver fibrosis, and the induction of inflammatory cytokine and neutrophils recruitment were IL-17A-dependent." (PMID 32513305, 2020). "The critical role of IL-17A signaling in the pathogenesis of liver fibrosis was previously suggested." (PMID 30346985, 2018). "Recent studies illustrated the crucial role that IL17A plays in the development and progression of hepatic fibrosis, along with the anti-fibrotic activity of BM-MSCs." (PMID 30346985, 2018). "We evaluated the effect of BM-MSCs administration to CCl4-induced liver fibrosis group on the expression of il17a/f isoforms and their receptors' (Il17a and Il17r) genes." (PMID 30346985, 2018). "In this study, we demonstrated a therapeutic potential of BM-MSCs in CCl4-induced rat liver fibrosis through inhibition of IL17A/F isoforms expressed genes and IL17 associated signaling pathway." (PMID 30346985, 2018). "Several studies have referred to interleukin 17A (IL17A) as a critical key player in liver fibrosis." (PMID 30346985, 2018).
liver fibrosis (continued). "Interleukin-17A has been identified as a driver of hepatic stellate cell activation and plays a critical role in the pathogenesis of hepatic fibrosis." (PMID 28039485, 2017). "Treg cytokine IL-10, which has been coupled with the activation of JAK-STAT1 or STAT3 signaling cascade and found high expression in liver fibrotic tissues, was used to reverse therapeutic effect of IL-17A antibody in TAA-induced hepatic fibrosis mice." (PMID 28039485, 2017). "Blocking IL-17A activity shows a therapeutic efficacy against both cholestatic and hepatotoxic hepatic fibrosis and results in a shift from the suppressive immune response toward a Th1 response in the fibrotic liver." (PMID 28039485, 2017). "The functional significance of IL-17A was evaluated in bile duct ligation (BDL) or thioacetamide (TAA) injection-induced mouse models of hepatic fibrosis." (PMID 28039485, 2017). "Taken together, these findings indicate that IL-10/STAT3 activation mediates IL-17A-suppressed autophagy and participates in the development of hepatic fibrosis." (PMID 28039485, 2017). "Recent studies have demonstrated that IL-17A plays a crucial role in the development and progression of tissues fibrosis including hepatic fibrosis." (PMID 28039485, 2017). "Interleukin 17a (IL-17a), the characteristic cytokine of Th17 cells, is a known hepatic fibrosis inducer that mediates ECM remodelling." (PMID 28465467, 2017). "When we depleted the Vγ2 T cells in infected mice, the percentage of neutrophils in blood and spleen decreased significantly, the liver fibrosis in the granulomas was reduced, and the level of IL-17A in the serum decreased (P < 0.05)." (PMID 28507072, 2017). "Altogether, these findings indicate that the phosphorylation of STAT3 mediates the IL-17A-suppressed autophagy of hepatocytes, which is involved in the development of hepatic fibrosis." (PMID 28039485, 2017). "Our study indicates that antagonism of IL-17A attenuates liver fibrosis by restoring the STAT3-suppressed autophagy flux in the BDL-and TAA-induced fibrotic liver tissues." (PMID 28039485, 2017). "We further examined the role of the endogenous IL-9 in hepatic fibrosis and its relationship with other relevant cytokines, including IL-17A, IFN-γ, TGF-β1, IL-6, IL-4, IL-21 and TNF-α in response to hepatic fibrosis, by neutralizing IL-9 in a mouse model." (PMID 26728971, 2016). "Plasma concentrations of IL-9 and IL-17A were both remarkably higher in mice with liver fibrosis than in controls." (PMID 26728971, 2016). "Liver fibrosis and IL-17A production by γδ T cells were both significantly attenuated in toll-like receptor (TLR)-3 KO mice compared with wild-type mice." (PMID 27824548, 2016). "Splenic Th9 and Th17 cells, plasma concentrations and liver expression of IL-9 and IL-17A were significantly elevated in mice with hepatic fibrosis compared with controls." (PMID 26728971, 2016). "Cytokines CXCL-11, INF-γ, and IL-17A are associated with liver inflammation, whereas CXCL-10, IL-2R, TGF-α, and IL-8 are correlated with liver fibrosis in chronic HBV-infected patients." (PMID 26559292, 2015). "In a CCl4-induced mouse model of liver fibrosis, exosome-mediated activation of Toll-like Receptor 3 in HSCs during the early stages of liver injury promoted the progression of liver fibrosis by enhancing the production of IL-17A from Gamma Delta T cells." (PMID 39995661, 2025). "Interestingly, IL-17A antibody treatment improved liver fibrosis in 10 psoriasis patients, highlighting its potential as a therapeutic target for anti-fibrotic therapies." (PMID 39995661, 2025). "This study indicates that IL17-related genetic polymorphisms and metabolic characteristics significantly affect liver fibrosis progression in MASLD patients, with the IL17A-G197A gene polymorphism identified as an independent multivariate predictor of fibrosis progression." (PMID 40332363, 2025).
liver fibrosis (continued). "Interestingly, evidence in other liver diseases, such as alcohol-associated liver disease and viral hepatitis C, suggest a correlation of IL-17A expression and liver fibrosis." (PMID 38829197, 2024). "In addition, IL-17a can also facilitate liver fibrosis by promoting HSCs activation, an observation suggesting the at least partially essential role of IL-17a in the occurrence of HCC." (PMID 38740736, 2024). "Nevertheless, the overall descriptive nature of our study does not allow us to firmly conclude on a causal link between IL-17A and liver fibrosis in patients." (PMID 36625344, 2023). "We therefore hypothesized that NKG2D-dependent induction of IL-17A expression mediates liver fibrosis in the context of MAFLD." (PMID 37774007, 2023). "Nevertheless, the level of Il-17A expression might be a precursor marker of liver fibrosis and could be a target for anti-fibrotic liver treatment." (PMID 36077175, 2022). "Most studies on IL-17A and liver fibrosis have been conducted on a mouse model." (PMID 36077175, 2022). "This might be explained by the relatively high dose of Sj cercariae infection inducing a more severe extent of liver fibrosis, and the major production of IL-17A from γδT cells in Sj-infected mice spleen." (PMID 35461268, 2022). "Knowing the advances of IL-17A studies in hepatic fibrosis, we decided to verify whether IL-17A acts on the expression of fibrotic and pro-inflammatory markers in human tissue." (PMID 36077175, 2022). "IL-17A-dependent hepatic stellate cell activation is critical for liver fibrosis." (PMID 34804155, 2021). "Moreover, it was shown that in the early stage of liver injury, exosome-mediated TLR3 activation in HSCs aggravates the development of liver fibrosis by enhancing IL-17A Tγδ-cell production in CCl4 mouse fibrosis model." (PMID 34211477, 2021). "Furthermore, in mice infected with Schistosoma japonicum, Vγ2 γδ T cells recruit neutrophils to granuloma and the liver by producing IL-17A, thereby aggravating liver fibrosis." (PMID 33869241, 2021). "During liver fibrosis, these are key molecules upregulated by IL-17A, thus it can be speculated that disruption of RA signaling will extend the deleterious effects of IL-17A." (PMID 34211477, 2021). "However, very few studies have examined the relationship of this IL-17A-AR-IL-22 trio in the context of liver fibrosis." (PMID 34211477, 2021). "Increased IL-17A is also found in mouse models of Alzheimer’s diseases and hepatic fibrosis." (PMID 33292701, 2020). "Furthermore, mice with defective IL-17A signaling (by IL-17A knockout or IL-17A neutralization, or by enhancing the dominance of immunosuppressive Treg) were protected from liver fibrosis and NAFLD progression." (PMID 33013934, 2020). "Taken together, we speculate that IL-17A may recruit CD11b+Gr-1+ cells and promote liver fibrosis by expressing TGF-β." (PMID 32611373, 2020). "We next examined whether IFNγ or IL-17 is responsible for the development of liver fibrosis by comparing the degree of liver fibrosis upon in vivo blockade of IFNγ and IL-17A in WT and TCRδ−/− mice mice." (PMID 30930903, 2019). "However these data contradict with findings in lung and hepatic fibrosis where IL-17A neutralization resulted in an amelioration of fibrosis." (PMID 31296924, 2019). "Similarly, IL-23 driven ILC3 production of IL-17A and IL-22 during hepatitis B virus (HBV) infection has been shown to be associated with liver fibrosis in human patients, with liver cirrhosis potentially driven by the recruitment of Th17 cells." (PMID 30893756, 2019). "Collectively, we suggest that BM-MSCs might play an immunomodulatory role in the treatment of liver fibrosis through downregulation of IL17A affecting IL6/STAT3 signaling pathway." (PMID 30346985, 2018). "Thus, we suggest that BM-MSCs ameliorate liver fibrosis via downregulation of IL17A dependent IL-6/STAT3 signaling pathway." (PMID 30346985, 2018).
liver fibrosis (continued). "To further understand whether Th17 CD4+-T cells are involved in the pathogenesis of hepatic fibrosis, we investigated the role of IL-17A in relation to S. mansoni disease severity." (PMID 29610679, 2018). "Indeed, our current study has further explored the mechanism of IL-17A in the regulation of hepatic fibrosis and provides insights for answering these questions." (PMID 28039485, 2017). "Furthermore, the relevance of these results showed that increased levels of IL-21 or IL-17A were positively correlated with liver fibrosis progression." (PMID 29192177, 2017). "Nonetheless, it remains unclear whether hepatocytes directly respond to IL-17A stimulation and are involved in the development of hepatic fibrosis." (PMID 28039485, 2017). "The second results from the evidence that activated HSCs exacerbate liver fibrosis by enhancing IL-17A production by T cells, in a TLR3-dependent manner, that in combination with the rarefaction of retinoic acid results promoting further Treg/Th17 imbalance and fibrogenesis." (PMID 29033929, 2017). "In summary, our current study not only indicates the IL-17A/STAT3 pathway playing a critical role in the pathogenesis of hepatic fibrosis, but also provides the proof of concept for this pathway acting as a potential therapeutic target against hepatic fibrosis." (PMID 28039485, 2017). "The mRNA levels of IL-9 and IL-17A were higher in mice with liver fibrosis than in controls." (PMID 26728971, 2016). "Furthermore, we found that percentages of splenic Th9 and Th17 cells, plasma concentrations and liver expression of both IL-9 and IL-17A were significantly higher in mice with hepatic fibrosis than in controls." (PMID 26728971, 2016). "Both IL-17a and IL-6 have been correlated with severe liver conditions, such as liver fibrosis, which may contribute to MHE34." (PMID 26757951, 2016). "Furthermore, plasma levels of IL-9 and IL-17A were significantly correlated with the percentages of splenic Th9 and Th17 cells in mice with hepatic fibrosis, respectively." (PMID 26728971, 2016). "Neutralization of IL-9 in mice ameliorated hepatic fibrosis, attenuated the activation of hepatic stellate cells, reduced frequencies of Th9, Th17 and Th1 cells in spleen, and suppressed expression of IL-9, IL-17A, IFN-γ, TGF-β1, IL-6, IL-4 and TNF-α in plasma and liver respectively." (PMID 26728971, 2016). "Based on our results and the published data, we propose that activation of lymphocytes, particularly T helper cells expressing IL-17A and IFN-γ, may be pathogenically linked to the progressive hepatic fibrosis in chronic HCV infection." (PMID 27428948, 2016). "Significant differences were also noted for the G allele of the IL17F-A7448G (adjusted p = 0.0003) and the A allele of the IL17A-G197A gene polymorphisms (adjusted p = 0.0338), which were more common in patients with advanced liver fibrosis than in those with no fibrosis." (PMID 40332363, 2025). "Furthermore, IL-17A antibody therapy ameliorated hepatic fibrosis in a NASH mouse model." (PMID 39995661, 2025). "In the multivariable ordinal logistic model, only the IL17A-G197A gene polymorphism was significantly associated with a higher liver fibrosis stage (adjusted p = 0.0155); none of the other metabolic or genetic factors demonstrated a significant association with an increased liver fibrosis stage." (PMID 40332363, 2025). "Additionally, IL-17A stimulates the proliferation and collagen synthesis of HSCs and upregulates the expression of matrix metalloproteinases (MMPs), influencing extracellular matrix remodeling and accelerating the progression of liver fibrosis." (PMID 40399593, 2025). "In vivo experiments demonstrated that blocking IL-17 with anti-IL-17A mAb significantly improved liver function and decreased hepatocellular necrosis, pro-inflammatory cytokines, neutrophils and macrophages influx in bile duct ligation-induced liver fibrosis mice." (PMID 33841164, 2021).